SH2D3A (SH2 domain containing 3A)
Description:
May play a role in JNK activation.
Synonyms: NSP1
Tractability: PROTAC: ubiquitination databases record sites on it.
Gene: Protein-coding gene on chromosome 19 (6,752,160 to 6,768,109, reverse strand). Ensembl gene ENSG00000125731.
Subcellular location (Human Protein Atlas): Microtubules; Cytokinetic bridge; Nucleoplasm
Gene Ontology:
Molecular function: protein binding; guanyl-nucleotide exchange factor activity; phosphotyrosine residue binding
Biological process: JNK cascade; small GTPase-mediated signal transduction
Genetic constraint (gnomAD): Loss-of-function variants: 48 observed, 47.38 expected, observed/expected ratio (o/e) 1.01, 90% interval 0.8 to 1.29. The upper end of that interval is the gene's LOEUF score, 1.29, which puts it in group 5 of 6, group 1 being the genes least tolerant of losing a copy. Missense variants: 783 observed, 721.52 expected, observed/expected ratio (o/e) 1.09, 90% interval 1.02 to 1.15. Synonymous variants: 377 observed, 321.7 expected, observed/expected ratio (o/e) 1.17, 90% interval 1.08 to 1.28.
Homologues: Orthologues: chimpanzee SH2D3A (99% identical), macaque SH2D3A (94% identical), pig SH2D3A (83% identical), guinea pig SH2D3A (78% identical), dog SH2D3A (76% identical), Drosophila melanogaster CG9098 (28% identical). Paralogues in human: BCAR3 (39% identical), SH2D3C (35% identical).
Diseases named in the same sentence as SH2D3A in open-access papers:
SH2D3A is named in the same sentence as 33 diseases in open-access papers, as found by Europe PMC text mining. Sharing a sentence is not in itself a finding about the gene and the disease. The quoted sentences say what the papers report.
breast carcinoma (2 papers, 2024 to 2025). "The top five hub genes for the hormone-like community were KRT18, JUP, KRT8, SH2D3A and PDLIM1; KRT18 and KRT8 are luminal markers in breast cancer while JUP (plakoglobin), SH2D3A and PDLIM1 are relatively undescribed in the context of cancer." (PMID 39556603, 2024).
colorectal cancer (2 papers, 2022). A primary or metastatic malignant neoplasm that affects the colon or rectum. "Finally, high expression of SH2D3A has been reported to enhance the progression of ovarian cancer, and downregulation of PHLDA2 has been reported to significantly inhibit the development of colorectal cancer through the PI3K/AKT signaling pathway." (PMID 35712127, 2022).
ovarian carcinoma (2 papers, 2022). A malignant neoplasm originating from the surface ovarian epithelium. "In ovarian cancer, the miR-1205/SH2D3A axis modulates cell growth, migration and invasion." (PMID 35674190, 2022).
pancreatic tumors (1 paper, 2022). "Analysis of the expression level of the hub genes indicated that the genes TNNT1, KCNN4, SH2D3A, and PHLDA2 were differentially expressed between 179 pancreatic tumors and 171 normal tissue samples." (PMID 35712127, 2022). "The expression level of genes TNNT1, KCNN4, SH2D3A, and PHLDA2 was significantly different between the 179 pancreatic tumors and 171 normal tissue samples." (PMID 35712127, 2022).
cancer (4 papers, 2017 to 2024). A tumor composed of atypical neoplastic, often pleomorphic cells that invade other tissues. "Among other genes in the modules, SH2D3A, AP1M2, CDS1 and SCNN1A haven’t been previously studied in cancer biology." (PMID 28651527, 2017).
SH2D3A also shares sentences with these, for which no sentence is quoted: infection (150 papers); viral infection (46); COVID-19 (25); SARS-CoV infection (5); Rotavirus infection (4); co-infection (3); amyotrophic lateral sclerosis (2); diarrheal disease (2); influenza (2); lung carcinoma (2); pneumonia (2); tumor (2); Acute hepatitis (1); Alzheimer disease (1); asthma (1); biliary atresia (1); brain tumor (1); Cognitive Deficits (1); hemorrhage (1); Hepatitis (1); hepatocellular carcinoma (1); infectious disease (1); liver disease (1); melanoma (1); myeloid leukemia (1); neurodegenerative disease (1); pancreatic disease (1); Parkinson disease (1).